FASN (fatty acid synthase)
Diseases named in the same sentence as FASN in open-access papers (continued):
Sharing a sentence is not in itself a finding about the gene and the disease.
melanoma (continued). "In summary, we reported that IT exerted anti-melanoma activities, and these effects were partially due to inhibition of FASN/IGF-1R/STAT3 signaling." (PMID 27323414, 2016). "Fatty acid synthase (FASN) is a key molecule associated with increased proliferation, survival, and drug resistance in various cancer cells including melanoma." (PMID 27980732, 2016). "Melanoma cells grown under these conditions develop chemo-resistant phenotype, characterized by increased expression of FASN, Cav-1, and P-gp." (PMID 27980732, 2016). "Collectively, these results suggest that increased levels of FASN, Cav-1, and P-gp in tumors are associated with increased tumor growth and impairment in the outcome of DTIC therapy in melanoma under obese state." (PMID 27980732, 2016). "Cav-1 and FASN were found to be co-expressed and related to poor prognosis in patients with pancreatic adenocarcinoma, and a high-fat diet led to upregulation of Cav-1 and FASN and rapid proliferation of melanoma cells." (PMID 27331874, 2016). "Melanoma tumors exhibit reduced expression of Mov10 compared with benign nevi and Mov10 levels inversely correlate with FASN levels in primary tumors." (PMID 26029828, 2015). "We observed high-Mov10-expressing cells are most commonly benign tumors with low FASN expression, whereas low-Mov10-expressing tumors with high FASN expression were more often malignant melanoma." (PMID 26029828, 2015). "We previously reported that two FASN inhibitors, cerulenin and orlistat, induce apoptosis in B16-F10 mouse melanoma cells via the intrinsic apoptosis pathway." (PMID 24964211, 2014). "Recently, we demonstrated the release of mitochondrial cytochrome c in the FASN inhibition-induced apoptosis of B16-F10 melanoma tumor cells." (PMID 24964211, 2014). "Recently, it has been reported that FASN and Cav-1 interact together and modulate each other in melanoma cells." (PMID 23613870, 2013). "Fatty acid synthase over-expression in melanoma has been correlated with Breslow thickness and overall poor survival." (PMID 24039618, 2013). "In the field of targeted therapy, experimental studies have described that FASN inhibitors reduce tumor progression in other tumors and could reduce metastasis in models of melanoma cells." (PMID 40867038, 2025). "Distribution of FASN expression level in melanomas classified according to the site of origin." (PMID 40867038, 2025). "Indeed, fatty acid synthase (FASN) is overexpressed in several cancers, and its inhibitors have been reported to reduce melanoma cell proliferation and activate the intrinsic pathway of apoptosis." (PMID 40867038, 2025). "Using orlistat to inhibit FASN activity in B16-F10 mouse melanoma cells triggers the intrinsic apoptosis pathway, characterized by cytochrome c release and the activation of caspase-9 and -3, and it is accompanied by increased ROS production and elevated cytosolic calcium levels." (PMID 38921444, 2024). "It was verified that in the case of malignant melanoma, there may be overexpression of metabolic genes such as fatty acid synthase (FASN) and acetyl-coA carboxylase (ACC)." (PMID 38928466, 2024). "In detail, by looking at individuals undergoing surgery for skin lesions suspected of melanoma, in subjects diagnosed with melanoma by pathological analysis (PT DH I/II), the plasma levels of FASN were shown to be significantly higher compared to all the other groups (Tukey p-values < 0.01)." (PMID 38338838, 2024). "In this way, we hypothesized that FASN-inhibition may render melanoma cells more sensitive to ROS by increasing the relative amount of membrane PUFA-phospholipids." (PMID 37072838, 2023). "We noticed that mature adipocytes express a high level of selected adipokines (leptin, adiponectin, resistin), lipid transport protein (FABP4), and enzymes related to lipid synthesis (FADS, SC4MOL, FASN), while their levels decrease in adipocytes cocultured with melanoma cells." (PMID 37481560, 2023).
melanoma (continued). "Moreover, the treatment of a melanoma mouse model (B16-F10 cells/C57BL/6 mice) with orlistat reduced lymph node metastases reinforcing the involvement of FASN in immune escape." (PMID 36934087, 2023). "Overall, we integrated genomic and clinical data from melanoma and NSCLC patients and found that FASN mutations might predict a preferable immunotherapeutic efficacy." (PMID 36428733, 2022). "Another inhibitor of FASN, orlistat, can suppress tumors by increasing CD8+ T cells and reducing T reg cells in a mouse melanoma model, demonstrating that FASN may be involved in tumor immunity regulation." (PMID 36555243, 2022). "Furthermore, our results showed that high FASN expression tended to be more responsive to immunotherapy in melanoma against different targets." (PMID 36555243, 2022). "We noticed that FASN is mutant in 60 of 631 melanoma samples (9.5%)." (PMID 36428733, 2022). "In this work, we consolidated genomic and clinical ICI data of melanoma and non-small cell lung cancer (NSCLC) samples, noticed that FASN mutations were linked to an elevated antitumor immunity, and were predictive of an improved ICI prognosis outcome and immunotherapeutic response rate." (PMID 36428733, 2022). "Similarly, the enhanced immune response ability of another FASN inhibitor, orlistat, was also revealed in melanoma." (PMID 36428733, 2022). "Spearman’s correlation between gene expression data of FASN and the IC50 values of PLX4720 (a structurally distinct analog of PLX4032) across BRAF-mutated melanomas indicated that FASN levels were inversely correlated with IC50 values both at gene (rs = −0.5) and protein level (rs = −0.53)." (PMID 34068792, 2021). "Downstream from FASN, saturated and unsaturated fatty acids are activated into fatty acyl-CoA by the acyl-CoA synthetase long-chain (ACSL) family members, and notably, ACSL3 expression has been associated with poor prognosis in melanoma patients." (PMID 34830962, 2021). "The expression of ACC1 and FASN is upregulated in human melanoma, as compared to conventional nevi." (PMID 33121001, 2020). "Elevated FASN activities in the more differentiated melanoma cell lines suggest that the FASN pathway may constitute a metabolic susceptibility in just those phenotypes." (PMID 32973134, 2020). "However, high doses of individual pharmacological inhibitors of SCD and FASN enzymes were reportedly required to impact cell viability in melanomas and other cancers." (PMID 31316083, 2019). "To get insights into the role of leptin and resistin in causing attenuation in the response to DTIC, we intended to analyze the status of FASN and Cav-1 which are upregulated in melanoma in the obese (HFD) mice, and are known to be involved in resistance to cancer chemotherapy." (PMID 29568521, 2018). "To confirm whether FASN and Hsp90 are involved in leptin-induced impairment in the response of melanoma cells to DTIC, we used their respective inhibitors." (PMID 29568521, 2018). "Western blot analysis showed that IT markedly inhibited FASN expression in melanoma cells." (PMID 27323414, 2016). "Therefore, it is likely that FASN, Cav-1, and P-gp are cumulatively responsible for impairment in the outcome of chemotherapy in melanoma." (PMID 27980732, 2016). "Cav-1 and FASN are coordinately regulated and Cav-1 interacts with FASN in melanoma cells." (PMID 26116372, 2015). "We asked whether the expression of FASN or SCD also correlated with Mov10 expression in human melanoma tumors." (PMID 26029828, 2015). "In contrast, high FASN activity is found in several neoplasias that occur in breast, ovarian, prostate, thyroid, lung, stomach, pancreas, colon, esophagus, mouth and bladder tissues, as well as soft tissue sarcomas and melanoma." (PMID 24964211, 2014). "Therefore, pharmacological inhibitors of FASN have attracted great attention as the suppression of FASN evidently inhibits the cell proliferation and escalates the rate of apoptosis all together in human and mouse melanoma cells." (PMID 31030489, 2019).
melanoma (continued). "Thus, the mutual involvement of FASN and Hsp90 could contribute to the unresponsiveness of melanoma cells to DTIC in the presence of leptin." (PMID 29568521, 2018). "Furthermore, fatty acid synthase inhibition induced apoptosis in melanoma cells." (PMID 28005927, 2016). "FASN inhibitors (e.g., TVB-2640, IPI-9119) suppress melanoma cell proliferation, induce endoplasmic-reticulum stress, and promote apoptosis." (PMID 41596686, 2026). "Dysregulation in lipid metabolism, particularly involving FASN and DHCR24, correlates with melanoma status and plasma lipid levels." (PMID 41596686, 2026). "In human melanoma, the expression of ACC1 and FASN is higher compared to that observed in common nevi." (PMID 41596686, 2026). "Supporting documents showed that FASN inhibition by CER slows proliferation of various cancer cells, including breast, colorectal, glioma, liver, and melanoma." (PMID 40133683, 2025). "A recent study in melanoma shows that BCAT-IN-2 leads to fewer colonies forming in vitro and reduces aberrant FASN and ACLY expression." (PMID 40507232, 2025). "In melanoma, increased BCAA metabolism leads to higher expression of FASN and ACLY genes, suggesting higher de novo lipogenesis." (PMID 40507232, 2025). "Distribution of Adipophilin, FASN, and HIF‐1α expression levels in non‐metastatic melanomas, metastatic melanomas, and cutaneous nevi." (PMID 40867038, 2025). "Among these, we detected co-upregulated melanoma marker gene MLANA and metabolic genes FASN, GPX3, and APOD, suggesting metabolic reprogramming as a key factor in invasiveness." (PMID 40866912, 2025). "For this reason, this study aimed to compare the immunohistochemical expression of adipophilin, FASN, GLUT‐1, and HIF‐1α across three aggressive types of melanomas." (PMID 40867038, 2025). "FASN and DHCR24 lipogenic enzymes were shown to be involved in the modulation of BRAFi response in melanoma." (PMID 38338838, 2024). "The expression of branched-chain amino acid transaminase 2 (BCAT2) also affects the levels of FASN and ACLY, promoting De Novo lipogenesis and facilitating melanoma progression." (PMID 38921444, 2024). "As the levels of the lipogenic enzymes FASN and DHCR24 differed in melanoma patients with respect to controls, we proceeded further to lipidomic profiling studies." (PMID 38338838, 2024). "We quantitatively assessed the levels of FASN and DHCR24 enzymes in melanoma patients and healthy control subjects in relation to plasma TG and CHOL and tested plasma lipid composition by untargeted/targeted lipidomic approaches." (PMID 38338838, 2024). "Recently, the enzyme BCKDHA, known as branched-chain keto acid dehydrogenase E1 subunit alpha, which is involved in branched-chain amino acid metabolism, has been found to regulate the expression of FASN and ATP-citrate lyase (ACLY) in melanoma." (PMID 38921444, 2024). "Leptin and resistin are both secreted by adipocytes and affect synthesis of FASN (fatty acid synthase) and the activation of the AKT-based signal transduction pathway, thus promoting the proliferation of melanoma cells." (PMID 37481560, 2023). "Melanoma cells led to a reduction of lipid content in CAAs, possibly by downregulation of lipid synthesis pathways (lower FADS, SC4MOL, FASN) or enhancement of lipolysis (higher level of phosphorylation of ERK and STAT3)." (PMID 37481560, 2023). "The relevance of SCD1, MVK, FASN and DHCR24 in melanoma progression or drug resistance is already supported by our previous studies and by the literature." (PMID 35912092, 2022). "Therefore, we integrated multiomics and immunotherapy data from melanoma and NSCLC samples, and found that FASN mutations could predict a preferable immunotherapeutic survival and response, which proposes a clinically potential indicator for choosing tumor patients to treat with immunotherapies." (PMID 36428733, 2022).
melanoma (continued). "Resistant melanoma cells displaying enhanced migratory and pro-invasive abilities increased sensitivity to the BRAF inhibitor PLX4032 upon the molecular targeting of FASN and upon treatment with the FASN inhibitor orlistat." (PMID 34068792, 2021). "Of note, we also checked cBioPortal and found that these proteins related to angiogenesis (i.e. FASN, CLIC4, HSPB1, ARHGEF1, PHGDH, MYO1C, CAV1) are altered in a total of 242 melanoma patients out of a total of 471 (51.36%)." (PMID 31142788, 2019). "Therefore, we examined if inhibition of FASN could suppress IGF-1R expression in melanoma." (PMID 27323414, 2016). "This suggests that altered levels of adipocyte-secreted factors are involved in modulating FASN, Cav-1, and P-gp levels which, in turn, influence the outcome of DTIC therapy in melanoma cells." (PMID 27980732, 2016). "Our studies indicate that Mov10 shRNA increases expression of FASN and SCD in cultured melanoma cell lines promoting Wnt5a secretion." (PMID 26029828, 2015). "Our finding that FASN and Cav-1 interact is an indicative of similarities in the modulation of FASN by Cav-1 and vice versa between HCC cells and melanoma." (PMID 23613870, 2013). "Barcode group 2 uniquely expressed lipid metabolism genes, such as FASN and APOE, which contribute to melanoma resistance by promoting MAPK inhibitor resistance through reducing lipid poly-unsaturation and protecting MITF^low/AXLĥigh persister cells from ferroptosis, respectively." (PMID 41000875, 2025). "Specifically, we showed that the combination of BRAFi with inhibitors of lipogenic enzymes fatty acid synthase (FASN) and 24-dehydrocholesterol reductase (DHCR24) resulted in favorable drug interactions, potentially exploitable for the treatment of BRAFi-resistant melanoma." (PMID 38338838, 2024). "Fluvastatin and cerulenin, which target HMGCR and FASN, respectively, were drugs approved for non-cancer-related diseases that reduced viability of melanoma cell lines." (PMID 37495601, 2023). "Fatty acid synthase (FASN), the rate limiting enzyme in FA synthesis, is upregulated in many cancer types, including melanoma, due to constitutive activation of the transcription factor sterol regulatory element-binding protein 1c (SREBP1c) driven by the MAPK and PI3K/AKT pathways." (PMID 33498757, 2021). "Four DNFA enzymes – SCD, FASN, ACLY and ACSS2 – exhibit the highest levels of mRNA expression in skin cutaneous melanoma (SKCM) compared to other tumor types, whereas expression of ACACA is less elevated in melanomas." (PMID 31316083, 2019). "When the secondary tumors are excluded, there is a negative correlation between Mov10 and FASN expression levels in melanoma tumors (r= −0.27; P<0.01; N=141)." (PMID 26029828, 2015). "Quantification of Mov10 and FASN levels reveal a negative correlation between Mov10 and FASN protein expression in primary melanoma and benign tumors." (PMID 26029828, 2015). "Because FASN inhibitors also induced apoptosis in the melan-a cells, the non-tumorigenic melanoma cell counterpart, the percentage of cytochrome c released was also determined in these cells." (PMID 24964211, 2014). "Most mucosal melanomas (> 80% of cases), regardless of the site of origin, showed FASN expression." (PMID 40867038, 2025). "Interestingly, the inhibition of FASN with orlistat, a FDA-approved anti-obesity drug, or with cerulenin, significantly reduces metastases and angiogenesis in a mouse syngeneic model of melanoma." (PMID 36934087, 2023). "FASN has been shown to be expressed in melanoma, but its relation to drug resistance is not known." (PMID 34068792, 2021). "Lipid metabolism genes such as fatty acid synthase (FASN) and 24-dehydrocholesterol reductase (DHCR24) have been proposed to contribute to tumor aggressiveness, but the therapeutic value of lipid metabolism inhibitors, particularly in drug-resistant melanoma, is unknown." (PMID 34068792, 2021).
Insulin resistance (60 papers, 2010 to 2025). Increased resistance towards insulin, that is, diminished effectiveness of insulin in reducing blood glucose levels. "One of the 6 signals was cg06906087 in the FASN gene, which has previously been associated with insulin resistance." (PMID 35843982, 2022). "There is increasing evidence that FASN is associated with DM and insulin resistance." (PMID 38272906, 2024). "In addition, increased FASN expression in human adipose tissues is linked to insulin resistance and inflammation." (PMID 38168040, 2024). "FASN DNA methylation exhibited putative causal effects on VF that were also strongly associated with insulin resistance and methylation levels in FASN better classified insulin resistance (AUC=0.91) than BMI or VF alone." (PMID 35843982, 2022). "Furthermore, FASN DNA methylation also exhibited putative causal effects on VF that were also strongly associated with insulin resistance, such that methylation in FASN was a better classifier of IR than BMI alone." (PMID 35843982, 2022). "They found that a deficiency of FASN specifically in macrophages could help protect against diet-induced insulin resistance and inflammation." (PMID 29463677, 2018). "Among these KOs, fatty acid synthase is involved in multiple metabolic pathways such as fatty acid biosynthesis, mycolic acid biosynthesis, fatty acid metabolism, and insulin resistance." (PMID 40461531, 2025). "Fatty acid synthase (FASN), a key enzyme of hepatic DNL, is upregulated in association with insulin resistance." (PMID 37681411, 2023). "The improvement in insulin resistance via inhibition of sterol regulatory element binding protein-1c and fatty acid synthase ameliorates hepatic steatosis." (PMID 38129407, 2023). "The protective effect of TRIM21 overexpression on HFD-induced glucose intolerance and insulin resistance was partially abolished by PEPCK1 or FASN overexpression." (PMID 37249651, 2023). "Only expression of ACACA and FASN are significantly decreased in obese subjects with insulin resistance." (PMID 37047391, 2023). "FASN, the key protein in lipid metabolism, has proved to be closely connected to insulin resistance by research that in adipose tissue, FASN expression was increased and insulin sensitivity was impaired." (PMID 36157445, 2022). "Circulating FASN has been previously proposed as a biomarker for overnutrition-induced insulin resistance." (PMID 35843982, 2022). "Methylation at cg11950105 in FASN combined with BMI was a strong predictor of insulin resistance with an average AUC of 0.91." (PMID 35843982, 2022). "We also obtained evidences in this sense, as we find a trend of association (p < 0.1) between FASN mRNA expression in PBMC and triglyceride-glucose index, considered a marker of insulin resistance." (PMID 34526523, 2021). "Studies have shown that LPL and FASN over-expression result in higher fat mass and more insulin resistance." (PMID 27777604, 2016). "It is reported that the stimulation of FASN activity and the expression of FASN gene can induce the increase of body fat through regulating metabolic consequences of caloric excess such as insulin resistance, dyslipidaemia and altered adipokine serum profile." (PMID 25752448, 2015). "We now add chronic infection with HIV/HCV as a novel pro-insulin resistance setting in which serum FASN concentration is significantly increased." (PMID 20707918, 2010). "Moreover, TRIM21 mediated alleviation of hepatic lipid deposition and improvement of insulin resistance and glucose intolerance was partially abolished in the presence of FASN." (PMID 37249651, 2023). "Furthermore, SAT methylation levels in FASN were strongly predictive of insulin resistance status, significantly more so than BMI alone." (PMID 35843982, 2022). "Additionally, genetic alterations in these genes are strongly involved, especially mutations in five genes (DGAT1, FASN, LPL, IRS2, and YWHAZ), in lipid synthesis, insulin resistance, and cancer progression." (PMID 31717414, 2019).